WNT5A (Wnt family member 5A)
Diseases named in the same sentence as WNT5A in open-access papers (continued):
Sharing a sentence is not in itself a finding about the gene and the disease.
ovarian carcinoma (continued). "In our study, we described that Wnt5a expression was significantly higher in normal ovaries than in ovarian carcinomas with a proportion of 70% to 44.3%." (PMID 30079293, 2018). "In the current study, the methylation status of Wnt5a in the human epithelial ovarian cancer was determined by MSP analysis." (PMID 30079293, 2018). "Further studies are needed to determine if Wnt5a is responsible for the influence that ROR1 apparently has on the biology of ovarian cancer stem cells." (PMID 28491097, 2017). "An early study of primary ovarian tumors (n = 130) that showed low levels of Wnt5a in ovarian cancer relative to normal ovary is predictive of a poor outcome." (PMID 28491097, 2017). "Compared with the frequency of Wnt1 expression in ovarian cancer, Wnt5a was more frequently found in malignant epithelial ovarian cancer patients (80% out of a total 38)." (PMID 28491097, 2017). "Of note, patients with ovarian cancers that express high levels of both Wnt1 and Wnt5a had a significantly lower probability of long-term survival than patients with ovarian cancers that did not express Wnt1 or Wnt5a." (PMID 28491097, 2017). "The correlation between Wnt5a signaling and senescence was demonstrated for the first time in ovarian cancer." (PMID 27571105, 2016). "Such a Wnt5a/PKC-promoted EMT was also found in epithelial ovarian cancer and oral squamous cell carcinoma (OSCC)." (PMID 27895670, 2016). "In contrast, high Wnt5a staining in ovarian cancer relative to normal ovary was found to correlate with poor prognosis in two related studies." (PMID 27571105, 2016). "Our previous study and other studies demonstrated a promoting role of Wnt5A in epithelial ovarian cancer." (PMID 28536612, 2016). "With respect to the chemoresistance, Wnt5a has been suggested as a biomarker of poor clinical outcome of patients with ovarian cancer and a mediator of chemoresistance." (PMID 27895670, 2016). "In this article, we review findings regarding the molecular mechanisms and roles of Wnt5a signaling in various cancer types, and highlight Wnt5a in ovarian cancer." (PMID 27571105, 2016). "A previous study revealed that a Wnt5b orthologue Wnt5a suppress ovarian cancer cells, and our data revealed that Wnt5a showed relative higher expression in ovarian cancer cells than that of Wnt5b (data not shown)." (PMID 27072580, 2016). "We recently reported that the Wnt ligand, Wnt5a, is upregulated in ovarian cancer patients and modelling this in vitro leads to increased cell proliferation and migration." (PMID 26515598, 2015). "We have previously shown in a large patient cohort that Wnt5a is upregulated in epithelial ovarian cancer compared to healthy controls." (PMID 26515598, 2015). "Here we investigated the role of two Wnt receptor tyrosine kinases (RTKs), ROR1 and ROR2, and their putative ligand, Wnt5a, in ovarian cancer." (PMID 26515598, 2015). "Ovarian cancer that overexpressed Wnt5A also showed lower chemosensitivity to paclitaxel, oxaliplatin, 5-fluorouracil, epirubicin and etoposide." (PMID 25401518, 2014). "RhoA and Wnt-5a mRNA and protein expression were quantified in normal fallopian tube epithelium, benign cystadenoma (serous and mucinous), primary ovarian carcinomas, and metastatic omentum using real-time polymerase chain reaction (PCR) and western blotting." (PMID 24351810, 2013). "RhoA and Wnt-5a mRNA and protein expression in normal fallopian tube epithelium, benign tumors, primary ovarian carcinomas, and metastatic omentum were quantified." (PMID 24351810, 2013). "RhoA mRNA expression was significantly positively correlated with Wnt-5a mRNA expression in ovarian carcinoma (p = 0.001, R2 = 0.1669)." (PMID 24351810, 2013). "RhoA or Wnt-5a was knocked down in OVCAR3 ovarian carcinoma cells using siRNAs and cell phenotype and expression of relevant molecules were assayed." (PMID 24351810, 2013). "RhoA mRNA expression was positively correlated with that of Wnt-5a mRNA in ovarian carcinoma tissue." (PMID 24351810, 2013).
ovarian carcinoma (continued). "To study the molecular mechanisms, we observed the effects of RhoA or Wnt-5a knockdown on the phenotypes and expression of molecules regulated in ovarian carcinoma cells in vitro." (PMID 24351810, 2013). "RhoA and Wnt-5a expression were positively correlated in ovarian carcinoma (p = 0.001, R2 = 0.1669)." (PMID 24351810, 2013). "Knockout of Wnt5a in host cells dramatically reduces tumor burden and alters immune infiltration patterns, suggesting that targeting Wnt5a or its downstream effector, Fgr, may be an effective therapeutic strategy for halting ovarian cancer metastasis." (PMID 40330466, 2025). "It has been indicated that Wnt5a could facilitate VM development in epithelial ovarian cancer via the PKCalpha pathway." (PMID 40497987, 2025). "Moreover, analysis of the Australian Ovarian Cancer Study data indicated that high expression of WNT5A resulted in a significantly higher expression of CSC markers." (PMID 38191909, 2024). "Increased WNT5A expression has been shown to induce epithelial to mesenchymal transition across multiple cancer types (breast, lung and colon), and in cell lines taken from hepatocellular and ovarian cancer." (PMID 39164966, 2024). "Moreover, ovarian cancer cell lines, characterized by high levels of Wnt5a expression, have shown lower sensitivity to several drugs (paclitaxel, oxaliplatin, 5-FU, epirubicin, and etoposide)." (PMID 36672361, 2023). "In this paper, we investigate whether Wnt5A is associated with the TGF-β1/Smad2/3 and Hippo-YAP1/TAZ-TEAD pathways, implicated in epithelial to mesenchymal transition (EMT) in epithelial ovarian cancer." (PMID 35053353, 2022). "Furthermore, increased expression of Wnt family member 5A (Wnt5a) correlates with enhanced metastasis of ovarian cancer via increased vasculogenic capacity, motility, and invasiveness." (PMID 36358843, 2022). "WNT5A has been shown to regulate ovarian cancer invasion and migration." (PMID 34017835, 2021). "Ovarian cancer cells overexpressing Wnt5a showed low chemosensitivity to paclitaxel and epirubicin." (PMID 34047951, 2021). "This supports the hypothesis that Wnt5A modulates cell proliferation and migration of ovarian cancer cells through up-regulation of ITGAV expression." (PMID 33723319, 2021). "The result indicated that miR-1180 could activate Wnt signal pathways because Wnt5a, β-catenin, myc and cyclinD1 levels increased in ovarian cancer cells with miR-1180 and SFRP1 overexpression." (PMID 30936781, 2019). "However, some scholars have found that when compared to a benign epithelial neoplasia group and normal ovary group, the proportion of Wnt5a-positive women was significantly higher for the epithelial ovarian cancer group." (PMID 30079293, 2018). "Wnt5a gene region promoter aberrant methylation existed in epithelial ovarian cancer, and abnormal methylation of Wnt5a gene promoter regions may be a new target for the treatment of epithelial ovarian cancer." (PMID 30079293, 2018). "Over-expression of Wnt5a mediates VM formation in ovarian cancer and lung cancer." (PMID 28320399, 2017). "Furthermore, Wnt5a is prevalent in ascites fluid obtained from women with ovarian cancer, suggesting that it contributes to the ovarian tumor microenvironment." (PMID 28491097, 2017). "Furthermore, ovarian cancer cell lines that have high levels of Wnt5a expression showed lower chemosensitivity to paclitaxel, oxaliplatin, 5-fluorouracil, epirubicin and etoposide." (PMID 27571105, 2016). "It has been demonstrated that Wnt5A is involved in inflammatory processes but its role in ovarian cancer in relation to inflammation remains unknown." (PMID 28536612, 2016). "For example, a recent study showed a Wnt5a immune-modulatory role in ovarian cancer cells." (PMID 27571105, 2016). "In addition, siRNA was used to silence ROR1, ROR2 and Wnt5a individually, and together, in two ovarian cancer cell lines, and the effects on cell proliferation, adhesion, migration and invasion were measured." (PMID 26515598, 2015).
ovarian carcinoma (continued). "Upregulation of Wnt5A was found in oxaliplatin-resistant ovarian carcinoma cell line." (PMID 25401518, 2014). "We investigated the roles of RhoA and Wnt-5a in ovarian carcinoma." (PMID 24351810, 2013). "The functional experiments also suggested that Wnt-5a knockdown attenuated the aggressiveness of ovarian carcinoma, including proliferation, anti-apoptosis, migration, and invasion, by modulating phenotype-related molecules such as Akt, PI3K, Bcl-xL, VEGF, p70S6k, and survivin." (PMID 24351810, 2013). "However, the role of these transcription factors in the regulation of Wnt5A in human ovarian cancer remains unknown." (PMID 28536612, 2016). "In addition, we also sought to determine the therapeutic potential of targeting these receptors by performing an extensive suite of in vitro experiments, exploring the functional role of ROR2, its sister receptor, ROR1 and putative ligand, Wnt5a in ovarian cancer." (PMID 26515598, 2015). "The therapeutic potential of targeting YAP/TAZ and related signaling molecules such as Wnt5A, ET-1, AREG, and ECM components offers promising avenues for improving outcomes in ovarian cancer patients." (PMID 40630468, 2025). "Wnt5a enhanced vasculogenic mimicry, EMT, migration, and invasiveness of ovarian cancer cells in a PKCα-dependent manner, and inhibition of PKCα blocked these effects." (PMID 36358843, 2022). "Silencing Wnt5A by siRNAs significantly decreased Smad2/3 activation and YAP1 expression and nuclear shuttling in ovarian cancer (OvCa) cells." (PMID 35053353, 2022). "In the current study, we found that miR-30a-mediated DEGs are involved in the regulation of key biological processes of ovarian cancer, such as SOX9, transcription factor 21 (TCF21), Wnt-5a,etc." (PMID 33004058, 2020). "Ectopic expression of Wnt5a inhibits the proliferation of human ovarian cancer cell line OVCAR5 both in vitro and in vivo orthotopic ovarian cancer mouse models." (PMID 28491097, 2017). "PKCα has been shown to be involved with Wnt5a in EMT and VM in ovarian cancer cells, where the expression of Wnt5a and PKCα were correlated and PI3K levels were enhanced upon up-regulation of Wnt5a." (PMID 28320399, 2017). "miR-217 was suggested to be a tumor suppressor by targeting Wnt5a in osteosarcoma and targeting IGF1R in ovarian cancer." (PMID 28437471, 2017). "WNT-1 expression has been detected in ovarian carcinomas; however, other WNT ligands were also found such as WNT-5a, which was highly expressed in EOC tumours." (PMID 24499657, 2014). "For instance, in ovarian cancer, miR-365 has been found to regulate SKOV3 cells proliferation, colony formation, migration, and invasion through targeting and inhibiting the expression of WNT5A." (PMID 33928018, 2020). "In this study, we aimed to understand whether inflammatory mediators such as lipopolysaccharide (LPS), lipoteichoic acid (LTA) or recombinant human IL-6 (rhIL-6) can modulate Wnt5A and ROR2 expression in the human ovarian cancer cell line SKOV-3." (PMID 28536612, 2016). "Moreover, another study on ovarian carcinoma showed that Wnt5a signaling through Ror1 and Ror2 receptors induced EMT and enhanced ovarian cancer cells migration and in trans-well assay." (PMID 27571105, 2016). "Furthermore, Wnt5a enhanced the vasculogenic mimicry, EMT, motility and invasiveness of ovarian cancer cells in a PKCα-dependent manner." (PMID 27571105, 2016). "This study revealed for the first time that inflammatory mediators modulate Wnt5A and ROR2 through NF-kB and STAT3 transcription factors and this may play a role in ovarian cancer cell migration." (PMID 28536612, 2016). "In addition, it has been shown that WNT5A may mediate vasculogenic mimicry and EMT in ovarian cancer cells via PKC-α signaling." (PMID 34017835, 2021). "Similarly, WNT5A in the ascites of HGSOC induces the formation of metastatic peritoneal implants by promoting ovarian cancer cell adhesion to the peritoneum, as well as ovarian cancer cell migration and invasion." (PMID 32560059, 2020).
ovarian carcinoma (continued). "Conversely, studies on noncanonical Wnt/β-catenin signaling show that Wnt5a may regulate ovarian cancer EMT, migration, or metastasis via noncanonical signaling pathways." (PMID 28491097, 2017).
colorectal cancer (49 papers, 2009 to 2025). A primary or metastatic malignant neoplasm that affects the colon or rectum. "Further, in colorectal cancer, WNT5A methylation is associated with tumour microsatellite instability, and therefore is particularly prone to replication errors and is predictive of response to chemotherapy and immunotherapy." (PMID 39164966, 2024). "IL-10 promotes Wnt5a-induced M2 polarization of tumor-associated macrophages, promoting the progression of colorectal cancer." (PMID 37341987, 2023). "WNT5A can also induce polarization of tumor-associated macrophages (TAMs) and ultimately promoting tumor growth and metastasis of colorectal cancers." (PMID 37722040, 2023). "Association of Wnt-5a mRNA isoforms expression and clinical parameters in tumor tissues of colorectal cancer patients." (PMID 28859077, 2017). "In colorectal cancer, where Wnt5a acts as a tumor suppressor and its loss is correlated with metastasis and poor survival rate, it was shown that Wnt5a enhanced epithelial characteristics and downregulated mesenchymal traits, suggesting a reversal of EMT." (PMID 27571105, 2016). "In contrast, Wnt5a heterozygous mice are predisposed to develop B cell lymphoma through loss of Wnt5a function, and WNT5A gene inactivation by somatic deletions or hypermethylation is frequent in human leukemia, lymphoma and colorectal carcinoma." (PMID 24260410, 2013). "Low or loss of expression of WNT-5A is linked to increased metastatic and invasive phenotype and poor prognosis in breast and colorectal cancers, whereas in thyroid cancer, it may have tumor-suppressor activity despite its increased expression." (PMID 26514730, 2016). "Promoter methylation of WNT-5A is associated with distinct tumor subtypes in colorectal cancer." (PMID 26514730, 2016). "In contrast, other studies have reported that Wnt5a promotes epithelial–mesenchymal transition and contributes to colorectal cancer progression and metastasis." (PMID 41008809, 2025). "In colorectal cancer, Wnt5a has been reported to act as either an oncogene or a tumor suppressor, depending on the downstream pathway activation." (PMID 41008809, 2025). "In the progression of colorectal cancer, Wnt5a demonstrates diverse roles across various signal transduction pathways." (PMID 39200196, 2024). "Study has clarified that WNT5A is highly expressed in CAFs in colorectal cancer and promotes the progression of colorectal cancer." (PMID 39054546, 2024). "On the other hand, the presence of the Wnt5a protein appears to decrease, as it is commonly deactivated in colorectal cancer (CRC) through tumor-specific methylation." (PMID 39200196, 2024). "CCL2 was also reported require for colorectal cancer progression, which was secreted by Wnt5a+ TAMs." (PMID 38576043, 2024). "It has been reported that DNA methylation of the genes MGMT and WNT5A indicates an excellent response to 5‐FU‐based therapy in colorectal cancer." (PMID 38778448, 2024). "CAF-derived WNT5A has recently been highlighted to play a crucial role in colorectal cancer progression by increasing tumor cell proliferation and migration." (PMID 37566084, 2023). "In colorectal cancer, M2-TAMs induced by Wnt5a-mediated CaKMII-ERK1/2-STAT3 pathway-mediated IL-10 secretion can significantly promote the growth and metastasis of intestinal cancer cells." (PMID 36160004, 2022). "In colorectal cancer, including the spectrum from normal colorectal adenoma to cancer, infiltrating macrophages display high levels of Wnt2 and Wnt5a." (PMID 34579753, 2021). "This review summarizes the recent findings on the clinical importance and function of Wnt5a in the pathogenesis of colorectal cancer (CRC)." (PMID 34603445, 2021). "Using TCGA colorectal cancer RNAseq and protein expression data, we demonstrated that WNT5A and TGFB1 were positively correlated with SMARCD3; WNT5A and TGFB1 were overexpressed in SMARCD3 high group." (PMID 33125346, 2020).